ZNF677 (zinc finger protein 677)
Description:
May be involved in transcriptional regulation.
Synonyms: MGC48625
Tractability: PROTAC: ubiquitination databases record sites on it.
Gene: Protein-coding gene on chromosome 19 (53,235,381 to 53,254,898, reverse strand). Ensembl gene ENSG00000197928.
Subcellular location: Nucleus
Subcellular location (Human Protein Atlas): Nucleoplasm; Centrosome
Pathways (Reactome):
Gene expression (Transcription): Generic Transcription Pathway
Gene Ontology:
Molecular function: DNA-binding transcription factor activity, RNA polymerase II-specific; RNA polymerase II cis-regulatory region sequence-specific DNA binding
Biological process: regulation of transcription by RNA polymerase II; regulation of DNA-templated transcription
Cellular component: nucleus
Genetic constraint (gnomAD): Loss-of-function variants: 5 observed, 8.74 expected, observed/expected ratio (o/e) 0.57, 90% interval 0.3 to 1.2. That is too few expected variants to judge how well the gene tolerates losing a copy. Missense variants: 685 observed, 719.4 expected, observed/expected ratio (o/e) 0.95, 90% interval 0.89 to 1.01. Synonymous variants: 221 observed, 238.99 expected, observed/expected ratio (o/e) 0.92, 90% interval 0.83 to 1.03.
Homologues: Orthologues: chimpanzee ZNF677 (99% identical), macaque ZNF677 (96% identical), rabbit ZNF677 (75% identical). Paralogues in human: ZNF429 (45% identical), ZNF708 (44% identical), ZNF724 (43% identical), ZNF568 (43% identical), ZNF726 (43% identical), ZNF85 (43% identical), ZNF7 (42% identical), ZNF254 (42% identical), ZNF728 (42% identical), ZNF471 (41% identical), ZNF28 (41% identical), ZNF43 (41% identical), and 164 more.
Diseases named in the same sentence as ZNF677 in open-access papers:
ZNF677 is named in the same sentence as 29 diseases in open-access papers, as found by Europe PMC text mining. Sharing a sentence is not in itself a finding about the gene and the disease. The quoted sentences say what the papers report.
thyroid cancer (7 papers, 2021 to 2022). "Additional results suggested that the reduced abundance of ZNF677 in thyroid cancer was caused by methylation-induced inhibition of the promoter in the ZNF677 gene." (PMID 35406382, 2022). "Further support for a role of ZNF677 in Akt phosphorylation was generated in experiments in which ZNF677 was overexpressed in cultured thyroid cancer cells." (PMID 35406382, 2022). "Inhibition of Akt phosphorylation by zinc finger protein 677 suppresses proliferation, colony formation, and tumorigenic potential and induces apoptosis and cell cycle arrest in thyroid cancer cells." (PMID 35256924, 2022). "Recent studies in thyroid cancer demonstrated that ZNF677 functions as a tumor suppressor and is frequently silenced through promoter methylation." (PMID 34785764, 2021). "Based on ZNF677 expression, we identified three ZNF677-expressing thyroid cancer cell lines (8505C, Cal-62, and BHT-101) and six thyroid cancer cells with loss of ZNF677 expression (ML-1, TT609, CGHT-W1, BCPAP, TPC-1, and K1)." (PMID 34360599, 2021). "Previous studies report that ZNF677 is frequently silenced by promoter methylation in non-small cell lung cancer and thyroid cancer." (PMID 34360599, 2021). "A previous study demonstrated that ZNF677 inhibits proliferation, migration, and invasion of thyroid cancer cells and exerts its tumor suppressor functions by inhibiting the phosphorylation of AKT via transcriptional repression of its two downstream targets, CDKN3 and HSPB1 (or HSP27)." (PMID 34360599, 2021). "In addition, a previous report showed that ZNF677 inhibits AKT phosphorylation in thyroid cancer." (PMID 34360599, 2021). "Moreover, hypermethylation of ZNF677 was reported to decrease ZNF677 expression, which could serve as a prognostic markers in several malignancies including lung cancer and thyroid cancer." (PMID 34360599, 2021). "Previous studies have confirmed that the PI3K/AKT signaling pathway is crucial in ZNF677-mediated invasion and EMT of thyroid cancer cells." (PMID 35164660, 2022). "In an attempt to explore the role of ZNF677 in PTC cell growth, we first analyzed the basal expression of ZNF677 in a panel of nine thyroid cancer cell lines by immunoblotting." (PMID 34360599, 2021). "Previous studies demonstrated that ZNF677 inhibits proliferation, migration, invasion and EMT progression of thyroid cancer cells." (PMID 34785764, 2021). "In addition, one study demonstrated that zinc finger protein 677 (ZNF677) functioned as a tumour suppressor and was frequently silenced via promoter methylation in thyroid cancer." (PMID 35678231, 2022).
non-small cell lung carcinoma (6 papers, 2015 to 2022). A group of at least three distinct histological types of lung cancer, including non-small cell squamous cell carcinoma, adenocarcinoma, and large cell carcinoma. "ZNF677 is located at chromosomal region 19q13 and was found to regulate the putative tumor cell growth suppressor in non-small cell lung cancers through hypermethylation." (PMID 34778269, 2021). "Methylation was reported to be the main mechanism for downregulation of tumor cell growth suppressor ZNF677 in non-small cell lung cancers (NSCLCs) and the methylation of ZNF677 could be used in the prognosis of NSCLCs." (PMID 32064261, 2020). "In our study, we investigated the role of ZNF677 in non-small cell lung cancers (NSCLC)." (PMID 25504438, 2015).
renal cell carcinoma (5 papers, 2022 to 2024). "ZNF677 also inhibits the progression of renal cell carcinoma through the transcription of N6 methyladenosine and CDKN." (PMID 38720365, 2024). "Aolin Li and colleagues demonstrated that ZNF677 represses the malignant evolution of renal cell carcinoma through the reduction of CDKN3 expression." (PMID 38953023, 2024). "It has been proven that ZNF677 inhibits the progression of renal cell carcinoma through the transcription of N6 methyladenosine and CDKN3." (PMID 38720365, 2024). "The expression of ZNF677 and its clinicopathological impact were evaluated in renal cell carcinoma (RCC) patients." (PMID 35678231, 2022). "ZNF677 plays a tumor suppressor role in renal cell carcinoma (RCC) through transcriptionally repressing its downstream target CDKN3." (PMID 37264402, 2023).
Papillary Thyroid Carcinoma (3 papers, 2021). "We have previously reported that loss of ZNF677 expression promotes EMT and metastatic potential of papillary thyroid cancer cells." (PMID 34785764, 2021). "Functionally, we confirmed that ZNF677 was downregulated and inactivated by promoter methylation using MSP assays and that demethylation restored ZNF677 expression in papillary thyroid cancer cells, which is in accordance with previous reports." (PMID 34360599, 2021). "In addition, ZNF677 is frequently down-regulated by promoter methylation in primary papillary thyroid cancers (PTC), and the decreased expression of ZNF677 is significantly correlated with poor survival." (PMID 34778269, 2021). "Mechanistically, we demonstrated that ectopic expression of ZNF677 markedly inhibited proliferation, migration, invasion, and EMT progression of papillary thyroid cancer cells." (PMID 34360599, 2021).
clear cell renal cell carcinoma (2 papers, 2015 to 2022). "However, the expression and function of ZNF677 in clear cell renal cell carcinoma (ccRCC) are still unclear." (PMID 35164660, 2022).
lung carcinoma (2 papers, 2021). "Previous reports have highlighted the tumor suppressive role of ZNF677 in thyroid and lung cancer." (PMID 34785764, 2021).
lymph node metastasis (2 papers, 2021 to 2022). "This suggests that loss of ZNF677 expression is a useful biomarker to identify the high risk population with potential lymph node metastasis and acts as an independent risk factor for predicting lymph node involvement in CRC patients." (PMID 34785764, 2021). "Loss of ZNF677 expression was seen in 45.3% of CRCs and was significantly associated with adverse clinico-pathological factors including advanced stage and lymph node metastasis." (PMID 34785764, 2021). "We performed multivariate logistic regression analysis and found that indeed ZNF677 loss was indeed an independent predictor for lymph node metastasis in CRC (Odds ratio = 1.41; 95% confidence interval 1.05–1.87; p = 0.0203)." (PMID 34785764, 2021). "Since we found ZNF677 loss to be significantly associated with lymph node metastasis, we sought to determine whether ZNF677 loss could be utilised as a predictor of lymph node metastasis." (PMID 34785764, 2021). "We demonstrated that the complete loss of ZNF677 protein expression in our CRC patient cohort is significantly associated with aggressive clinico-pathological parameters and lymph node metastasis." (PMID 34785764, 2021). "The data showed that ZNF677 methylation was significantly positively associated with pathological T stage, Fuhrman classification, and lymph node metastasis but not with age, sex, smoking, and distant metastasis." (PMID 35164660, 2022). "Moreover, we explored the correlation between ZNF677 expression and clinico-pathological parameters and sought to determine if ZNF677 could be utilized as a biomarker to predict lymph node metastasis in CRC." (PMID 34785764, 2021).
breast carcinoma (1 paper, 2015). "In addition, we analysed ZNF677 methylation in cell lines of other tumor entities including breast cancer (N = 5), colon cancer (N = 2), ovarian cancer (N = 2), pancreatic cancer (N = 2) and head and neck cancer (N = 2) by MS-HRM." (PMID 25504438, 2015). "All these tumor cell lines except 1 breast cancer (MDA-MB-468) and 1 ovarian cancer (SCOV3) cell line were found to be ZNF677 methylated." (PMID 25504438, 2015). "Overall, these results suggest that methylation of the 5 ́ region of ZNF677 is responsible for ZNF677 silencing in many tumor cell lines of different entities including NSCLC, breast cancer, colon cancer, ovarian cancer, pancreatic cancer and head and neck cancer." (PMID 25504438, 2015).
gastric cancer (1 paper, 2022). A primary or metastatic malignant neoplasm involving the stomach. "Recent studies have demonstrated that ZNF677 is expressed at low levels and functions as a tumor suppressor in thyroid, lung, and gastric cancers as a result of DNA methylation." (PMID 35164660, 2022).
large cell carcinoma (1 paper, 2015). A malignant epithelial neoplasm composed of large, atypical cells. "We also investigated if downregulation of ZNF677 expression differs between NSCLC subtypes “adenocarcinoma” (ADC), “squamous cell carcinoma” (SCC) and “large cell carcinoma”." (PMID 25504438, 2015).
tumor (11 papers, 2015 to 2025). "To explore molecular mechanisms underlying tumour‐suppressive effects of ZNF677 in RCC, we first tested the effect of ZNF677 on the expression of downstream targets." (PMID 35678231, 2022). "We found not only that ZNF677 was more highly expressed in normal thyroid tissue than in tumor tissue, but also that loss of its expression was predictive of distant metastasis." (PMID 34360599, 2021). "Overall, our results indicate that ZNF677 is a potential tumor suppressor, and its loss of expression may lead to the activation of tumor-promoting pathways in PTC." (PMID 34360599, 2021). "The zinc finger protein ZNF677, a zinc finger protein family member, a tumor suppressor in ccRCC, is epigenetically regulated by METTL3." (PMID 40313614, 2025). "Recent studies have demonstrated that zinc-finger protein 677 (ZNF677) acts as a tumor suppressor gene in cancer." (PMID 35164660, 2022). "And we demonstrated that ZNF677 plays its tumour suppressor role in RCC through transcriptionally repressing its downstream target CDKN3." (PMID 35678231, 2022). "MeRIP‐qPCR assay confirmed that m6A level of ZNF677 was significantly lower in tumour tissues than normal tissues." (PMID 35678231, 2022). "Further, we provided compelling in vitro and in vivo evidences demonstrating that m6A can regulate the tumour growth of RCC via regulation of ZNF677 expression." (PMID 35678231, 2022). "RCC cells and subcutaneous models uncovered the role of ZNF677 methylated by CRISPR/dCas13b‐METTL3 in tumour growth." (PMID 35678231, 2022). "In summary, our findings revealed that ZNF677 is hypermethylated in ccRCC and that ZNF677 inhibits tumor cell proliferation and invasion, and induces apoptosis." (PMID 35164660, 2022). "To further determine the roles of CDKN3 in tumour‐suppressive effect of ZNF677 on RCC cells, we knocked down CDKN3 in OSRC and CAKI2 cells with ZNF677 deficiency." (PMID 35678231, 2022). "The results of the functional assays indicate that ZNF677 inhibits tumor cell proliferation and invasion and induces apoptosis." (PMID 35164660, 2022). "Combined with data from the TCGA database, the results of the present study demonstrated that ZNF677 acts as a tumor suppressor gene with significantly higher methylation in ccRCC tumor tissues than that in normal tissues." (PMID 35164660, 2022). "In this study, we provided strong evidences supporting that ZNF677 is a potent tumour suppressor in RCC." (PMID 35678231, 2022). "First, we identified many differentially methylated genes in RCC tumour tissues versus tumour‐adjacent normal tissues based on MeRIP‐seq technology and found that ZNF677 was frequently downregulated in RCC tumours." (PMID 35678231, 2022). "Consistently, xenograft model confirmed that m6A methylation of ZNF677 can inhibit tumour growth in vivo." (PMID 35678231, 2022). "Although the precise molecular mechanisms by which ZNF677 is involved in tumor invasion and EMT are currently elusive, activation of the PI3K/AKT signaling pathway has been reported to be involved." (PMID 35164660, 2022). "We analyzed tumor cell growth-suppressing properties of ZNF677 and its effects on proliferation and migration of PTC cells." (PMID 34360599, 2021). "These in vitro data provide additional evidence supporting a tumor suppressor role for ZNF677 in PTC." (PMID 34360599, 2021). "Our functional molecular results suggest that ZNF677 acts as a tumor suppressor, mediating its effect by inhibiting AKT phosphorylation." (PMID 34360599, 2021). "Previous evidence revealed that ZNF677 exerts its suppressor functions in tumor cells through interfering with phosphorylation and activation of AKT." (PMID 34360599, 2021). "Because of 2 public data onto overall survival be used, it seems like that hypermethylation of cg18335068 and lower expression of ZNF677 in OSCC are inconsistent with the tumor suppressor functions in other cancers." (PMID 32155325, 2020).
tumor (continued). "Overall, in NSCLC cell line experiments, we observed a strongly reduced tumor cell growth and reduced cell motility of ZNF677 overexpressing cells compared to control cells." (PMID 25504438, 2015). "Since we had ZNF677 identified to be tumor-specifically methylated in our genome-wide methylation analyses before, we used single-gene analyses to confirm methylation of ZNF677 in several NSCLC cell lines." (PMID 25504438, 2015). "To confirm tumor-specific downregulation of ZNF677 expression observed by gene expression microarray analyses, we additionally compared ZNF677 RNA-seq expression values in TU and NL samples of LUAD and LUSC datasets obtained from the Cancer Browser database." (PMID 25504438, 2015). "Overall, these data indicate that ZNF677 expression is tumor-specifically downregulated in different solid tumor types including NSCLCs." (PMID 25504438, 2015). "Differences in methylation between TU and NL samples were statistically significant (p = 1.3 * 10−20) demonstrating that ZNF677 is tumor-specifically methylated." (PMID 25504438, 2015). "We identified methylation as main mechanism for ZNF677 downregulation in NSCLC cells and we observed tumor-specific ZNF677 methylation in NSCLC patients (p < 0.0001)." (PMID 25504438, 2015). "Tumor-specific downregulation of ZNF677 expression in NSCLC patients was confirmed by RNA-seq expression values from the TCGA database." (PMID 25504438, 2015). "We also analysed TU and NL samples of a large number of NSCLC patients and identified statistically significant tumor-specific ZNF677 methylation." (PMID 25504438, 2015). "Overall, our results indicate that ZNF677 is frequently transcriptionally silenced by methylation in NSCLCs and they suggest that ZNF677 has tumor cell growth suppressing properties." (PMID 25504438, 2015). "In our study, we used these 2 datasets to search for tumor-specific differences of ZNF677 expression." (PMID 25504438, 2015). "Consistent to the data obtained by gene expression microarray analyses, a statistically significant tumor-specific downregulation of ZNF677 expression in NSCLC patients (p = 2.7 * 10−21) was found." (PMID 25504438, 2015). "Reduced tumor cell growth was observed in all 3 NSCLC cell lines analysed with 3 different assays which suggests that ZNF677 has intrinsic tumor cell growth suppressing function." (PMID 25504438, 2015). "Moreover, the expression of ZNF677 proteins gradually decreased from the primary tumor to metastatic tissues." (PMID 35164660, 2022). "In addition, ZNF677 exerted its tumour suppressor functions in RCC cells through transcriptional repression of CDKN3 via binding to its promoter." (PMID 35678231, 2022). "To evaluate the mRNA expression patterns of ZNF677 in ccRCC, we first used the TCGA data of 533 ccRCC tissues and 72 normal tissues available from the UALCAN platform and found that ZNF677 was considerably downregulated in tumor tissues compared to that in normal tissues." (PMID 35164660, 2022). "ZNF677 functions as a tumour suppressor and is frequently silenced via m6A modification in RCC, which may highlight m6A methylation‐based approach for RCC diagnosis and therapy." (PMID 35678231, 2022). "ZNF677 was significantly downregulated in tumour tissues compared with adjacent normal tissues." (PMID 35678231, 2022). "Our clinical and in vitro data suggest that ZNF677 is likely a tumor suppressor." (PMID 34360599, 2021). "Overall, our results demonstrate that ZNF677 is trancriptionally regulated by methylation in NSCLCs, suggest that ZNF677 has tumor cell growth suppressing properties in NSCLCs and that ZNF677 methylation might serve as prognostic parameter in these patients." (PMID 25504438, 2015). "ZNF677 methylation occurs tumor-specific in NSCLC patients and might be of potential prognostic impact for these patients." (PMID 25504438, 2015). "In addition, we analysed tumor cell growth suppressing properties of ZNF677 and determined molecular pathways which are affected by ZNF677." (PMID 25504438, 2015).
tumor (continued). "Because of heterogeneity of tumor cells within a tumor, we cannot exclude that heterogeneity of ZNF677 protein expression might have influenced our results." (PMID 25504438, 2015). "Moreover, we observed a strong tumor cell growth suppressing effect of ZNF677 and we identified certain pathways affected by ZNF677 which are involved in regulation of cell proliferation." (PMID 25504438, 2015). "Overall, these results demonstrate that ZNF677 is tumor-specifically methylated in NSCLC patients." (PMID 25504438, 2015). "We hypothesized that ZNF677 acts as a tumor suppressor in the progression of ccRCC." (PMID 35164660, 2022). "Moreover, our data showed inactivation of ZNF677 might be caused by significantly decreased enrichment of m6A methylation modification in its CDS and 3′UTR regions in tumour tissues." (PMID 35678231, 2022). "Thus, we investigated if ZNF677 has tumor cell growth suppressing properties." (PMID 25504438, 2015). "In vitro and clinical data confirm the negative roles of ZNF677/CDKN3 in tumour growth and progression of RCC." (PMID 35678231, 2022). "By comparing ZNF677 expression in primary tumor (TU) and in the majority of cases also of corresponding non-malignant lung tissue (NL) samples from > 1,000 NSCLC patients, we found tumor-specific downregulation of ZNF677 expression (adjusted p-values < 0.001)." (PMID 25504438, 2015).